NPY (neuropeptide Y)
Diseases named in the same sentence as NPY in open-access papers (continued):
Sharing a sentence is not in itself a finding about the gene and the disease.
adrenal cortical tumors (2 papers, 2012 to 2015). "In addition, a different study proposed a role of NPY in adrenal cortical tumors as well as a Y1R-mediated physiological role in the adrenal gland associated with strong NPY innervation of the cortex." (PMID 25624911, 2015).
alcohol-related disorders (2 papers, 2022 to 2023). Disorders related to or resulting from abuse or mis-use of alcohol. "Together, these results suggest that NPY-mediated inhibition of cortical circuits may play a role in the symptomatology observed in mood-and alcohol-related disorders and highlight the potential of NPY-based therapeutics for mental illnesses." (PMID 35800635, 2022).
allergic conjunctivitis (2 papers, 2011 to 2021). "Specifically, it has been demonstrated that neuropeptides, including substance P, calcitonin-gene-related peptide (CGRP), neuropeptide Y (NPY), and vasoactive intestinal peptide (VIP), play a key role in allergic conjunctivitis." (PMID 34685384, 2021).
angina (2 papers, 2019 to 2021). "Plasma NPY levels are increased in patients with acute myocardial infarction or angina, associated with tachycardia and left ventricular failure." (PMID 34344469, 2021).
autism spectrum disorder (2 papers, 2017 to 2021). A spectrum of developmental disorders that includes autism, and Asperger syndrome. "The observed pattern agrees with the role of DPP4 in processing the neuropeptides substance P and NPY and immune response and the proposed association with autism spectrum disorders." (PMID 33834688, 2021).
autonomic neuropathy (2 papers, 2018 to 2022). An inherited or acquired peripheral neuropathy affecting the autonomic nervous system. "It has even been suggested that basal NPY levels may be predictive of sympathetic nerve failure in patients with autonomic neuropathy." (PMID 30283345, 2018). "This includes NPY, and indeed reduced NPY levels in response to hypoglycaemia have been found in patients with autonomic neuropathy as opposed to without." (PMID 30283345, 2018).
carotid atherosclerosis (2 papers, 2009 to 2016). A thickening and loss of elasticity of the walls of carotid arteries that occur with formation of atherosclerotic plaques. "Previously, it has been reported that Leu7Pro substitution in the NPY gene has been associated with elevated levels of LDL cholesterol in cardiovascular diseases, carotid atherosclerosis." (PMID 27749914, 2016).
cerebrovascular disease (2 papers, 2021). "Studies clarifying the effect of NPY on the pathophysiological mechanism underlying chronic IH-induced vascular ED identify NPY as a potential target for the treatment of OSAS-related cerebrovascular diseases." (PMID 34512386, 2021).
coronary artery spasm (2 papers, 2018 to 2021). "NPY is highly vasoconstrictive, causing coronary artery spasms, and might be eventually related to the development of stress-related cardiomyopathy." (PMID 30237802, 2018). "It has been hypothesized that TTC patients experience excessive catecholamine and NPY release, with subsequent coronary vasospasm, leading to a pathological reduction in myocardial blood flow and alterations to parietal kinetics." (PMID 30237802, 2018).
cutaneous melanoma (2 papers, 2022 to 2023). A primary melanoma arising from atypical melanocytes in the skin. "A low NPY expression has been associated with scarce E-cadherin expression, high peritumoral mast cell infiltrates, and high cell proliferation in primary cutaneous melanomas." (PMID 37373115, 2023). "For example, NPY expression is associated with cutaneous melanoma." (PMID 35418942, 2022). "Evaluating the mechanistic role of NPY in cutaneous melanoma will determine whether this peptide may contribute or prevent disease and will indicate how this peptide could be targeted or used to combat disease pathogenesis and/or progression." (PMID 35418942, 2022). "Gilaberte and colleagues concluded that NPY may have a pro-tumorigenic role in cutaneous melanoma, and thus its high expression is an indication of poor prognosis for patients." (PMID 35418942, 2022). "Neither has GWAS analysis of cutaneous melanoma detected NPY as a susceptibility locus." (PMID 35418942, 2022). "Nevertheless, in a study in which copy number variations of neuropeptide and receptor genes were investigated for multiple cancers, the expression of NPY and its receptors, Y1R, Y2R, and Y5R, were given negative prognostic Z-scores in cutaneous melanoma." (PMID 35418942, 2022).
dyspepsia (2 papers, 2017 to 2024). An uncomfortable, often painful feeling in the stomach, resulting from impaired digestion. "With two-week TEA treatment, there was a notable decrease in dyspepsia symptoms and further increase in vagal activity, along with an elevation in serum neuropeptide Y (NPY) levels." (PMID 39062474, 2024). "Another clinical study applying TENS at ST36 in patients with functional dyspepsia also showed improved dyspeptic symptoms and increased high frequency heart rate variability possibly related to an increase in plasma neuropeptide Y level." (PMID 28883882, 2017).
endometriosis (2 papers, 2020 to 2024). The growth of functional endometrial tissue in anatomic sites outside the uterine body. "Notably, in women with endometriosis, there appears to be an elevated presence of neuropeptide Y (NPY) and vasoactive intestinal peptide (VIP) fibers within the functional layer of the endometrium." (PMID 38592287, 2024). "Compared with women without endometriosis, PGP9.5 (a highly specific pan-neuronal marker), NPY (a marker of sympathetic nerve fibers), and VIP (a marker of parasympathetic nerve fibers) positive nerve fibers are decreased in the isthmus of the oviduct of endometriosis patients." (PMID 32145751, 2020).
endotoxemia (2 papers, 2013 to 2022). "In models of endotoxemia, NPY can block monocyte induction and improve inflammatory measures." (PMID 23472120, 2013).
Ewing Sarcoma Family of Tumor (2 papers, 2022 to 2023). "In Ewing Sarcoma Family of Tumor (ESFT) cells, the knockdown of DPP4, DPP8, or DPP9 leads to NPY-mediated apoptosis." (PMID 37626841, 2023). "Endogenous NPY-driven cell death in Ewing sarcoma family tumors (ESFT) can be blocked by DPPs, including DPP8/9, which also indicates that NPY can serve as an in vivo substrate of DPP8/9." (PMID 36172198, 2022).
glucose metabolic disorders (2 papers, 2015 to 2020). "NPY may affect glucose metabolism by modulating the phosphorylation of PI3K, AKT and GSK3 in adipose tissue and adipocytes, and it is possible that the NPY Y5 receptor contributes to glucose metabolism disorder induced by NPY." (PMID 25993471, 2015).
head and neck cancer (2 papers, 2018 to 2023). A primary or metastatic malignant neoplasm affecting the head and neck. "The promoter methylation status of the NPY gene has been suggested as an epigenetic biomarker for head and neck cancer prognosis and risk." (PMID 37373115, 2023).
hepatic diseases (2 papers, 2019 to 2022). "This analysis revealed that not only is NPY elevated in the serum of patients with fibrotic liver diseases by 1.67-fold, but that the amount of NPY in serum also positively correlates with the severity of the liver disease." (PMID 35418942, 2022).
hyperandrogenism (2 papers, 2020 to 2023). Excessive secretion of androgens from the adrenal glands or gonads. "In hyperandrogenism, NPY in follicular fluid reduced androgen-induced apoptosis in autocrine manner as NPY receptors expression are higher, but not in the normal condition." (PMID 37653540, 2023). "However, prenatal androgen exposure that leads to postpubertal hyperandrogenism does not increase body weight and results in only very mild metabolic disturbances, suggesting that AR signaling is not elevating NPY activity." (PMID 33094210, 2020).
intracerebral haemorrhage (2 papers, 2023 to 2025). "In CSF, however, the day-by-day release of NPY was significantly increased in the SAH group compared to the intracerebral hemorrhage group and the control group, indicating that the hypersecretion of NPY into CSF, but not into serum, is specific for SAH." (PMID 38425753, 2023). "Furthermore, intracerebral haemorrhage patients with a good prognosis were reported to have lower serum NPY levels, suggesting the potential of NPY for predicting prognosis." (PMID 39575855, 2025).
intrauterine growth restriction (2 papers, 2023 to 2024). "There were abundant data indicating that intrauterine growth restriction exposure was associated with increased NPY levels." (PMID 37378669, 2024). "NPY also affects lung growth after intrauterine growth restriction, which is often caused by maternal alcohol consumption during pregnancy." (PMID 37836499, 2023).
irritable bowel syndrome (2 papers, 2021 to 2023). Irritable bowel syndrome (IBS) is a chronic functional condition of the lower gastrointestinal (GI) tract characterized by abdominal pain or discomfort and disordered bowel habit (diarrhea, constipation, or fluctuation between the two). "Fundamental investigations have indicated that the reduction of NPY levels in rats modeled with irritable bowel syndrome (IBS) might contribute to heightened stress responses and a cascade of inflammatory reactions, including visceral hypersensitivity." (PMID 37732301, 2023). "Neuropeptide Y (NPY) and vasoactive intestinal peptide (VIP) are two forms of neurotransmitter that play an important role in the pathogenesis of abnormalities in the brain-gut axis in irritable bowel syndrome (IBS)." (PMID 34211567, 2021).
lipodystrophy (2 papers, 2017 to 2025). A congenital or acquired disorder characterized by abnormal loss or redistribution of the adipose tissue in the body. "The results show that reestablishing hypothalamic NPY levels delayed aging-associated features, including lipodystrophy, alopecia, and memory." (PMID 40011349, 2025). "Here, we report that NPY deficiency in male mice during CR increases mortality in association with lipodystrophy." (PMID 28101970, 2017). "Importantly, the deficiency in adipose tissue content, a characteristic of the lipodystrophic phenotype, was reversed by hypothalamic NPY, emphasizing a potential avenue for improving lipodystrophy." (PMID 40011349, 2025). "Z24-KO mice exhibit severe lipodystrophy, which was improved upon NPY hypothalamic up-regulation." (PMID 40011349, 2025).
liver cirrhosis (2 papers, 2019 to 2022). "Moreover, we sought to investigate human circulating NPY levels and their relationship with the severity of liver cirrhosis." (PMID 31263154, 2019).
lung carcinoma (2 papers, 2021 to 2025). "We show that low BMI induces neuronal NPY secretion and promotes brain metastasis in lung cancer by reprogramming cancer cell energy metabolism, thereby facilitating tumor progression." (PMID 40595538, 2025). "Therefore, identifying an interventional agent that specifically blocks NPY’s effect on tumor cells would be a promising therapeutic approach to treat lung cancer brain metastasis." (PMID 40595538, 2025). "Interestingly, among all, only the active SREBP2 level was found to be upregulated in NPY-treated control cells, in contrast to untreated or Y5rKO cancer cells as well as in NPY-treated parental lung cancer cells." (PMID 40595538, 2025). "Notably, when lung cancer cells were treated with recombinant NPY (rNPY), they showed a dose-dependent increase in cell proliferation, growth kinetics and cell cycle progression." (PMID 40595538, 2025). "Similar results were obtained in murine and human lung cancer cell lines, both at transcript and protein levels, and its expression was significantly upregulated in the cancer cells in the presence of recombinant NPY." (PMID 40595538, 2025). "Furthermore, our study demonstrated a significant increase in tumor growth upon NPY treatment, along with an increased brain metastatic burden in a low BMI setting, indicating its distinct role in lung cancer progression beyond regulating feeding behavior and energy homeostasis." (PMID 40595538, 2025). "To further characterize the role of the Y5R in promoting low BMI-induced neuronal NPY-mediated tumor growth, we utilized CRISPR/Cas9 technology to knockout Y5r in a murine CMT167 lung cancer model." (PMID 40595538, 2025). "In lung cancer, evidence sentences were also found for all but three genes (BID, NPY, TPI)." (PMID 34653225, 2021).
metastatic disease (2 papers, 2015 to 2020). "Furthermore, our clinical data revealed a trend toward elevated NPY release in ES patients with metastatic tumors, as well as significantly higher systemic NPY levels in pelvic and axial ES of bone origin." (PMID 25714031, 2015). "Moreover, as Y5R and NPY expression have been shown in other metastatic tumors, blocking this pathway may become an effective anti-metastatic therapy for malignancies other than NB." (PMID 33681186, 2020).
neuroendocrine tumors (2 papers, 2010 to 2025). "Although neuroendocrine tumors, which synthesize and release endogenous NPY, seem the most susceptible to tumor growth regulation by this peptide, NPY and its receptors have also been implicated in nonneuronal types of tumors." (PMID 20508839, 2010).
osteosarcoma (2 papers, 2010 to 2017). A usually aggressive malignant bone-forming mesenchymal neoplasm, predominantly affecting adolescents and young adults. "Recently, the Y1 receptor was reported to be present in human osteoblastic and osteosarcoma-derived cell lines, and treatment of wild-type mice with NPY caused reduction in bone mass and volume." (PMID 20860441, 2010).
pituitary adenoma (2 papers, 2023). "Protein/mRNA NPY and mRNA Y1R/Y2R expressions have been reported in human pituitary adenomas; a positive correlation was also observed between Y2R and NPY levels." (PMID 37373115, 2023).
preeclampsia (2 papers, 2022). Preeclampsia is a hypertensive disorder of pregnancy that is characterized by new-onset hypertension with proteinuria presenting after 20 weeks of gestation, and depending on mild or severe forms may initially present with severe headache, visual disturbances, and hyperreflexia. "Some genes are noted to play key roles in preeclampsia, including LPAR4/5, CRLR, NPY, TACR1/2, and SFRP4/5, whose functions generally relate to angiogenesis and vasodilation or vasoconstriction." (PMID 35269385, 2022). "Systemic levels of neuropeptide Y (NPY), a peptide that acts as a sympathetic activator and vasoconstrictor, were found to be elevated in preeclampsia patients as compared to the normal pregnancy population." (PMID 35269385, 2022).
prostate tumor (2 papers, 2010 to 2023). "Studies in mice with xenografted prostate tumours have suggested that the mechanism underlying MIC-1-induced weight loss is hypophagia caused by reduced neuropeptide Y expression and increased pro-opiomelanocortin expression in the hypothalamic arcuate nucleus." (PMID 20104227, 2010). "NPY decreases prostate tumor cell proliferation (DU145 and LNCaP cell lines) and promotes cell proliferation in prostate PC3 tumor cells." (PMID 37373115, 2023). "Moreover, nerve fibers containing NPY have been involved in radiation therapy resistance because the apoptosis induced by radiation was decreased when prostate tumor cells were cocultured with dorsal root ganglia or nerve fibers." (PMID 37373115, 2023). "NPY also decreased the proliferation of specific prostate tumor cells." (PMID 37373115, 2023).
pulpitis (2 papers, 2022 to 2025). Inflammation of the dental pulp. "During irreversible pulpitis, Piezo2 downregulation occurs despite its strong association with pain mediators (neuropeptide Y (NPY), substance P, Tachykinin 1 (TAC1)) and overall pain intensity." (PMID 40708698, 2025). "In pulpitis, NPY Y1R is also found in infiltrating inflammatory cells, nerve fibers, and dental pulp fibroblasts, implicating its regulation of neurogenic inflammation." (PMID 36430624, 2022). "A variety of neuropeptides, including neurokinin A, substance P (SP), NPY, and CGRP, are shown to be upregulated in the pulp in conditions of caries, pulpitis, or occlusal trauma." (PMID 36430624, 2022).
sleep disorder (2 papers, 2025). A change from the patient's baseline sleeping pattern, in the hours slept and/or an alteration/dysfunction in the stages of sleep. "Ectopic expression of Mettl3 and NPY reduced neuroinflammation and neuronal loss and rescued the disrupted sleep behavior, suggesting that neuronal NPY is an essential regulator of sleep and may serve as a therapeutic target for patients with sleep disorders." (PMID 39905012, 2025). "Our results showed that Mettl3 loss leads to the decreased expression of NPY in neurons of VPM, and induces sleep disorder, especially NREM sleep disorder." (PMID 39905012, 2025). "Given the homology of the sNPF receptor to the receptor for NPY in mammals, understanding the sNPF system could provide important insight into the NPY system in humans, allowing for better understanding of sleep in humans and development of better treatments for sleep disorders." (PMID 39918815, 2025).
social anxiety disorder (2 papers, 2021 to 2025). "This further supports the potential benefit of NPY in disorders associated with social anxiety and fear and its potential as an alternative pharmacotherapy for social anxiety disorder patients who fail to respond to antidepressant treatments." (PMID 34576305, 2021). "We have previously shown that neuropeptide Y (NPY) reduces social fear in an animal model that closely mimics the key behavioral symptoms of social anxiety disorder (SAD)." (PMID 40490517, 2025).
ulcerative colitis (2 papers, 2024 to 2025). An inflammatory bowel disease involving the mucosal surface of the large intestine and rectum. "NPY expression was also reduced in the colon of WKY rats, consistent with findings in IBS patients with diarrhea and in ulcerative colitis patients and mice." (PMID 39346901, 2024).
viral infection (2 papers, 2021 to 2024). "Reduced NO output by the nasal epithelium with NPY elevations may contribute to susceptibility to both bacterial and viral infection." (PMID 34684394, 2021). "A protective role has been proposed for NPY regarding neurodegenerative/neuroimmune disorders and viral infections since it regulates calcium homeostasis, reduction of oxidative stress, protection from excitotoxic cell death, and neuroinflammation attenuation." (PMID 38793693, 2024).
withdrawal syndrome (2 papers, 2013 to 2014). "Because attenuated withdrawal syndrome is seen after intracerebroventricular application of NPY and because NPY is an orexigenic peptide, it can be hypothesized that NPY is involved in an endogenous counter-regulatory mechanism to opioid withdrawal." (PMID 23805290, 2013).
Zinc deficiency (2 papers, 2021 to 2024). A deficiency of the essential metal Zinc; an essential cofactor for many enzymes. "Zinc deficiency may contribute to these symptoms by reducing the activity of neuropeptide Y, an appetite stimulant, and impairing neurotransmitter function, potentially leading to refusal to feed." (PMID 39211658, 2024).
acute leukemia (1 paper, 2023). A clonal (malignant) hematopoietic disorder with an acute onset, affecting the bone marrow and the peripheral blood. "Plasma NPY and NPY mRNA levels in the bone marrow of children with acute leukemia have been studied." (PMID 37373115, 2023).
adrenal pheochromocytoma (1 paper, 2023). "Plasma NPY levels were higher in patients with adrenal pheochromocytoma than in healthy patients, or those with extra-adrenal pheochromocytoma, and tissue NPY levels were also higher in patients with adrenal pheochromocytoma than in those with extra-adrenal pheochromocytoma." (PMID 37373115, 2023). "It is important to note that the whole NPY1-36 molecule was the predominant form found in both plasma and tissue of patients suffering from adrenal pheochromocytoma; however, many NPY fragment types were reported in patients with extra-adrenal pheochromocytoma." (PMID 37373115, 2023).